CD86 (CD86 molecule)
Diseases named in the same sentence as CD86 in open-access papers (continued):
Sharing a sentence is not in itself a finding about the gene and the disease.
COVID-19 (continued). "Much like in severe COVID-19, hypersensitivity pneumonitis is characterized by a massive influx of activated T cells in the lungs and a high expression of B7 (i.e. mouse CD80/CD86 molecules) by alveolar macrophages." (PMID 34075090, 2021). "Conversely, post-COVID-19 subjects had normal proportions of monocyte subsets which had returned to a normal basal resting state and expressed the highest CCR2, CCR5, CD86 and HLA-DR levels on their surface." (PMID 34572439, 2021). "When compared to HC, monocytes from acute COVID-19 patients had higher size (FSC) and granularity (SSC), higher expression of CD11b, CD16 and CD33, similar expression of CCR2, CCR5 and CD86, and a marked downregulation of HLA-DR, as previously reported." (PMID 34572439, 2021). "The dysregulation of DC function in COVID-19 was also presented by the expression of the maturation marker (CD83), T-cell stimulation molecules (CD40, CD80, CD86) and antigen presentation molecules (HLA-DQA2 and FCER1A)." (PMID 34502134, 2021). "Namely, we found an enrichment of two COVID-19-unique inhibitory interactions between APCs and CD8+ T cells, CTLA4/CD86 and HAVCR2/LGALS9, which may be out of necessity to curb the heightened inflammation present in severe COVID-19." (PMID 36992700, 2023). "In response to in vitro stimulation with ligands for TLR3, TLR4, TLR7, or TLR8, the key populations of DCs from COVID-19 patients (i.e., pDC, cDC1, and cDC2) expressed less CD80, CD86, CCR7, and HLA-DR than the cells from corresponding populations of apparently healthy volunteers." (PMID 35632823, 2022). "Moreover, while CD80 was significantly upregulated in healthy, mild and moderate COVID-19 monocytes after SARS-CoV-2 stimulation, only healthy monocytes increased the expression of CD86 after stimulation." (PMID 36572683, 2022). "Moreover, dendritic cells, obtained from patients with COVID-19, expressed significantly less CD80, CD86, CCR7, and HLA-DR in response to in vitro stimulation compared to those from HDs." (PMID 36012146, 2022). "While differentiated DC subsets were reduced, we found that Lineage− HLA-DR+ CD86+/– CD45RA+/– proliferating cells lacking typical DC markers were greatly expanded in the blood of COVID-19 patients." (PMID 34614036, 2021). "However, in patients with severe COVID-19, monocytes and DCs in the blood were found to express lower levels of HLADR and CD86." (PMID 34614036, 2021). "Interestingly, post-COVID-19 monocytes showed the highest expression of CCR2, CCR5, CD86 and HLA-DR, and the lowest of CD11b." (PMID 34572439, 2021). "While increased CD38 expression across monocyte subsets was a general feature unrelated to disease severity, higher levels of CCR2 on iMonos, as well as lower levels of HLA-DR and CD86 with increased expression of CD163 in all monocyte subsets, were found in severe COVID-19." (PMID 33479167, 2021). "Amongst T-cell and monocytes/macrophages, some immune-stimulatory or auto-regulatory interactions were seen (CTLA4 or CD28/CD80 or CD86, CCL5/CCR5), but specific epithelial to T-cell interactions in critical COVID-19 were limited to pro-inflammatory ICAM1-mediated interactions." (PMID 33473155, 2021). "We found that SARS-CoV-2-S+ exosomes of MILD COVID-19 patients were mostly of B cell, dendritic cell, and monocyte/macrophage origin, as they displayed B-cell marker CD19, integrin CD11b, costimulatory molecule CD86, and MHC-class II HLA-DR." (PMID 35111156, 2021). "Due to the observed downregulation of CD86 and upregulation of PD-L1, DC3 and classical monocytes isolated from the blood of COVID-19 patients may be impaired in their ability to stimulate naïve CD4+ T cells." (PMID 34614036, 2021). "To explore whether the monocytes from COVID-19 patients exhibit a similar phenotype, we evaluated the expression levels of several activation markers, including CD33, CD86, CD80, HLA-DR, and CD40, in monocytes isolated from the peripheral blood mononuclear cells (PBMCs) of HD, MP and SP group." (PMID 39996729, 2025).
COVID-19 (continued). "We found that PD-1 expression in non-naïve CD8+ T cells correlated with PD-L1 expression and the PD-L1/CD86 ratio in mo 1 and to a lower extent also in DC3 (PD-L1: R = 0.34; p = 0.02, PD-L1/CD86: R = 0.37;p = 0.01) indicating potential interaction of this receptor ligand pair in COVID-19." (PMID 34614036, 2021). "Non-classical monocytes from both convalescent COVID-19 patients and uninfected controls demonstrated decreased CD56 and CD86 expression in response to LPS treatment." (PMID 38250080, 2023). "Downregulation of HLA-DR and CD86 in cell membrane and production of AREG are hallmarks of monocytic-myeloid derived suppressor cells which have been found expanded in circulation in severe and non-survivor COVID-19 patients." (PMID 34572439, 2021).
autoimmune disease (45 papers, 2006 to 2025). A disorder resulting from loss of function or tissue destruction of an organ or multiple organs, arising from humoral or cellular immune responses of the individual to their own tissue constituents. "Despite their structural similarities, CD80 and CD86 make distinct contributions to the development of pathogenic T cells in autoimmune diseases and protective T cells in infectious diseases." (PMID 27292320, 2016). "Furthermore, we identified clinically relevant mutations that cause autoimmune disease, which selectively disrupted CD86 transendocytosis, by affecting either CTLA-4 recycling or CD86 binding." (PMID 35999394, 2022). "Initially designed for treatment of autoimmune diseases (abatacept; approved for rheumatoid arthritis in 2005), it was mutated to induce higher avidity binding—especially for CD86—for the prophylaxis of organ rejection (belatacept; approved for renal transplantation in 2011)." (PMID 30057914, 2018). "As well as putative PCM1-JAK2 targets, shortlisted genes probably included those activated developmentally and pathologically by other means in CTCL cells, e.g. CD86 and HLA-DR loci, associated with antigen presenting cells and autoimmune disease, respectively." (PMID 23372669, 2013). "Our analysis suggests that the decreased CD80/CD86 ratio may be linked to the full development of the autoimmune disease, whereas the overexpression of CD40 pre-dates the occurrence of overt autoimmunity and may therefore be involved in its pathogenesis." (PMID 16507174, 2006). "We therefore propose that the decreased ratio of CD80 to CD86 in lupus DCs may be linked to the full development of the autoimmune disease, whereas the overexpression of CD40 may be important in the pathogenesis of this autoimmune disease." (PMID 16507174, 2006). "Dysregulation of CD80 and/or CD86 occurs in diverse autoimmune diseases, including EAE, RA, and EAU." (PMID 36739434, 2023). "Reduced expression of CD40 and CD86 can alleviate diseases such as chronic inflammatory disease and autoimmune disease because they are crucial for productive interactions between T cells and APCs cells." (PMID 38015971, 2023). "This assumption is consistent with the finding that overexpression of CD86 is correlated with the development of allergic and autoimmune diseases." (PMID 36271469, 2022). "A number of studies using clinical samples have suggested that overexpression of CD80 and CD86 is correlated with the development of allergic and autoimmune diseases." (PMID 36271469, 2022). "CD80 can promote T-cell differentiation to Th1, while CD86 can induce Th2-mediated humoral immune responses, which are crucially involved in the immune response of autoimmune diseases." (PMID 34925005, 2021). "It is a known fact that CTLA-4 Ig abatacept blocks CD28-mediated T cell activation by binding to the costimulatory B7 ligands CD80/CD86 on APCs, and it is currently used for RA and other autoimmune diseases." (PMID 32420329, 2020). "The loci identified included SNPs in immune response genes linked to autoimmune diseases including Crohn’s disease, ulcerative colitis, multiple sclerosis, and T1D (CD5, CCL2, IL23R, CD86, HLA, C11ORF30-LRRC32, CLEC16A)." (PMID 29454391, 2018). "PU.1 plays a crucial role in the regulation and expression of CD80, CD86, and cells in the hematopoietic system and it can also block several autoimmune diseases and even induce donor-specific tolerance to allograft." (PMID 26509179, 2015). "In vivo studies using anti-CD80 mAbs and anti-CD86 mAbs have suggested that CD80 and CD86 differentially regulate the development of autoimmune disease." (PMID 22997525, 2012). "Abnormal expression of CD80 and CD86 may lead to the initiation and exacerbation of autoimmune diseases." (PMID 32149157, 2020).
autoimmune disease (continued). "Given that endometriosis is an autoimmune disease, we speculate that the macrophages treated with serum of patients with endometriosis may simultaneously express CD86 and CD163, representing a special type of M2 macrophages." (PMID 30276219, 2018). "In addition, while CD80 and CD86 have been reported to play distinct functional roles in animal models of autoimmune disease, their individual contributions to shaping downstream T cell responses remain incompletely understood." (PMID 27898740, 2016). "Abatacept, a CTLA-4Ig costimulatory blockade that interferes with CD28 on T cells binding to CD80/CD86 on APCs, has shown efficacy in clinical trials for RA (which has become one of the established treatments), psoriatic arthritis, and juvenile idiopathic arthritis, among other autoimmune diseases." (PMID 38567291, 2024). "In this context, 111In-DOTA-belatacept could serve as a research tool to study the approach of targeting CD80/CD86-rich APCs in atherosclerosis and possibly other inflammation-related diseases such as cancer, autoimmune disease, and rejection after organ transplantation." (PMID 26728358, 2016). "Specifically, autoimmune-associated B cells (ABCs; defined as CD19+CD11c+) are a subset of potent APCs in autoimmune diseases, expressing high levels of CD80/CD86 and MHC class II." (PMID 41497588, 2025). "It has been shown that increased expression of CD80 and CD86 may be involved in the presentation of autoantigens and hyperactivation of T cells, in which the immune system attacks normal tissues and cells in the body, resulting in an exaggerated immune response in autoimmune diseases." (PMID 38361527, 2023). "B cells are believed to be important APCs in the pathogenesis of autoimmune diseases and express CD80/CD86 after activation; however, relatively little is known about the effect of CTLA-4-Ig on B cells." (PMID 32228715, 2020). "A Cytoscape network diagram in our study showed that PD-L2 in PDAC is closely related to the expression of PD-L1, CD86, TNFRSF14, PD-1, CD160 and CTLA-4, which are important for the regulation of immunodeficiency and autoimmune diseases." (PMID 31464648, 2019). "In contrast to the function of CD80/CD86, CTLA-4 can transmit an inhibitory signal to T cells to avoid some autoimmune diseases in normal people." (PMID 32793247, 2018). "Overexpression of co-stimulatory molecules such as CD86 has been shown to affect moDC from patients with SLE, an autoimmune disorder closely related to SS." (PMID 25113744, 2014). "In terms of cytokine/chemokines release, DSF could reduce expression of inflammatory cytokines and chemokines and reduced CD86 and MHC class II expressions during inflammation, autoimmune diseases, or tumors." (PMID 37326784, 2023). "Patients with HT were also characterized by an increased frequency of CD86+ non-classical Mo, which has been previously reported in patients with other autoimmune diseases including multiple sclerosis, systemic lupus erythematous, and primary biliary cirrhosis." (PMID 32153591, 2020). "Likewise, in the BXD2 mouse model of autoimmune disease, it has been reported that elevated expression of activation-induced cytidine deaminase (AID) in recirculating follicular CD86+ B cells and increased germinal centre activity are associated with the production of autoantibodies." (PMID 26290328, 2015). "In addition, the application of switch CAR/CCR T cell strategy to other areas such as B cell-mediated autoimmune diseases is also conceivable, as autoreactive B cells clusters with the most recently activated class-switched mBC (memory B cell) phenotype exhibit high CD80 and CD86 expression." (PMID 38340727, 2024). "However, in autoimmune diseases, the superior affinity of CTLA4 for its ligands led to the use of a CTLA4-immunoglobulin fusion protein (CTLA4-Ig) as an inhibitor of immune responses in vivo; the rationale being that it would bind to CD80 and CD86 and block their interaction with CD28." (PMID 26942414, 2017).
atherosclerosis (38 papers, 2014 to 2026). A disease characterized by the build-up of fatty material and calcium deposition in the arterial wall resulting in partial or complete occlusion of the arterial lumen. "The depletion of Tregs, through combined Cd80/Cd86 genetic deficiencies in mice, aggravates atherosclerosis." (PMID 37681883, 2023). "Due to the fact that deficiencies in the co-stimulatory molecules CD80 and CD86 have been shown to reduce atherosclerosis in mice, the surface expression of CD80 molecule on HUVECs was evaluated in the present study by assessing the MFI." (PMID 26622474, 2015). "A combined genetic Cd80/Cd86 deficiency revealed a lowered atherosclerotic burden in early atherosclerosis, which may be attributed to a reduction in lesional APCs as well as a T helper (Th) 1 response." (PMID 37681883, 2023). "However, a separate study found that Cd80/Cd86 deficiency reduced numbers of natural T regulatory (Treg) cells and led to increased atherosclerosis following 20 weeks of a high-fat, high-cholesterol diet." (PMID 37681883, 2023). "Mice deficient in CD80 and CD86 display reduced atherosclerosis and lower IFN-γ production by effector T cells, indicating that CD28-CD80/86 interactions prime T cells in atherosclerosis." (PMID 39817455, 2025). "IL-38 reduced the proportion of CD45+CD11b+F4/80+CD86+ M1-like macrophages, suggesting that IL-38 attenuates atherosclerosis by inhibiting M1-like macrophage polarization." (PMID 41463394, 2025). "Pharmacological inhibition of CD28-CD80/CD86 with the CTLA-4–Ig fusion protein abatacept reduced atherosclerosis in mice." (PMID 39817455, 2025). "Animal experiments demonstrated that CTLA4 binding to abatacept protein inhibits the interaction between CD28-CD80/CD86 to inhibit atherosclerosis." (PMID 36970364, 2023). "A study showed that CD80 and CD86 controlled the growth of atherosclerosis lesions and the activation of T cells that recognize lesional antigens." (PMID 36703734, 2022). "On the other hand, in human monocytes and monocyte-derived dendritic cells, the upregulation of α7-nAChRs and M1 marker CD40/CD86 enhances adaptive immunity in atherosclerosis, including T cell proliferation and cytokine production." (PMID 35096275, 2022). "In contrast, another study using irradiated BM chimeric mice of CD80/CD86 found a twofold increase in atherosclerosis accompanied by a decrease in Tregs." (PMID 33572939, 2021). "AsC treatment elevated Arg1 expression and reduced Cd86 expression in atherosclerosis, suggesting phenotypic switch to anti-inflammatory M2 macrophages." (PMID 31986489, 2020). "Flow cytometry analysis with live cells isolated from aorta tissue showed that the CD45+CD86+ (47.7%) or CD45+CD38+ (41.6%) M1 population in atherosclerosis specifically stained with CDg16 compared with the other CD45− cells." (PMID 30846702, 2019). "In the present proof-of-concept study, we evaluated the potential of CD80/CD86-specific belatacept for atherosclerosis imaging." (PMID 26728358, 2016). "111In-DOTA-belatacept accumulates in CD80/CD86-positive tissues in vivo and in vitro rendering it a research tool for the assessment of inflammatory activity in atherosclerosis and possibly other diseases." (PMID 26728358, 2016). "Other genes, such as FCER1G, might influence the formation of atherosclerotic plaques through antibody responses, while CD86 might affect atherosclerosis by mediating T cells/DCs activation." (PMID 41348730, 2025). "Our study showed that CD86 played a vital role in the pathogenesis of RA with atherosclerosis." (PMID 35304503, 2022). "In CD80–/–CD86–/–mice, the progression of atherosclerosis was delayed." (PMID 33613306, 2021).